TCP11X2 (t-complex 11 family, X-linked 2)
Tractability: No criterion of Open Targets' tractability assessment is met for any kind of drug.
Gene: Protein-coding gene on chromosome X (102,456,862 to 102,471,842, reverse strand). Ensembl gene ENSG00000215029.
Gene Ontology:
Biological process: regulation of sperm capacitation; signal transduction
Cellular component: acrosomal vesicle; sperm flagellum
Homologues: Orthologues: chimpanzee TCP11X2 (70% identical), rat Tcp11x2 (69% identical), mouse Tcp11x2 (63% identical), Caenorhabditis elegans M05D6.2 (25% identical), Drosophila melanogaster CG16721 (25% identical). Paralogues in human: TCP11X1 (99% identical), TCP11 (69% identical), TCP11L1 (37% identical), TCP11L2 (35% identical).
Diseases named in the same sentence as TCP11X2 in open-access papers:
TCP11X2 is named in the same sentence as 1 disease in open-access papers, as found by Europe PMC text mining. Sharing a sentence is not in itself a finding about the gene and the disease. The quoted sentences say what the papers report.
renal clear cell carcinoma (1 paper, 2019). "Two DEG were in common between the NPs and E171 exposure: TCP11X2, a T-complex family gene and KCCAT333, a renal clear cell carcinoma-associated transcript but the exact function of these 2 genes remains unknown." (PMID 31797963, 2019).